RCAN1 (regulator of calcineurin 1)
Diseases named in the same sentence as RCAN1 in open-access papers (continued):
Sharing a sentence is not in itself a finding about the gene and the disease.
ischemia (2 papers, 2012). A hypoperfusion of the BLOOD through an organ or tissue caused by a PATHOLOGIC CONSTRICTION or obstruction of its BLOOD VESSELS, or an absence of BLOOD CIRCULATION. "I/R-inducible expression of Rcan1 protein occurred mainly in astroglial cells, and in an in vitro model of ischemia, HGD treatment of primary murine astrocyte cultures induced Rcan1-4 mRNA and protein expression." (PMID 22397398, 2012).
ischemic stroke (2 papers, 2012). A stroke disorder caused by obstruction of blood flow to the brain, due to thrombotic (local blood clot formation) or embolic (due to a blood clot or other material traveling from another site) event. "Here, we have analyzed the role of endogenous regulator of CN 1 (Rcan1) in response to experimental ischemic stroke induced by middle cerebral artery occlusion." (PMID 22397398, 2012).
liver cancer (2 papers, 2021 to 2023). An epithelial or non-epithelial malignant neoplasm that arises from the liver. "Viewed in toto, these findings suggested that miR-182-5p/RCAN1 may have diagnostic potential in liver cancer, and RCAN1 was regulated by its upstream regulator miR-182-5p to act as a tumor suppressor." (PMID 33959160, 2021). "This study revealed, for the first time, the regulatory mechanism of the interaction between miR-182-5p and RCAN1 underlying the progression of liver cancer, which may provide superior treatment opportunities." (PMID 33959160, 2021). "RCAN1 is an endogenous protein that inhibits liver cancer cells’ proliferation, migration, invasion, and cell cycle progression." (PMID 37168369, 2023). "MiR-182-5p stimulated liver cancer cell proliferation by downregulating the regulator of calcineurin 1 (RCAN1)." (PMID 37168369, 2023). "In summary, our study conveyed that miR-182-5p fostered cell proliferation, migration, invasion, and cell cycle progression of liver cancer by targeting RCAN1 expression." (PMID 33959160, 2021). "Next, the expression of RCAN1 in human normal liver cell line HL-7702 and four liver cancer cell lines SMMC-7721, HepG2, Huh-7, and Hep3b was assessed via qRT-PCR." (PMID 33959160, 2021). "Initially, we learned from the data retrieved from the bioinformatics database that RCAN1 was particularly lowly expressed in liver cancer tissue." (PMID 33959160, 2021). "A large dozens of excellent reviews describe that RCAN1 significantly hampers cell proliferation, migration, and invasion of liver cancer." (PMID 33959160, 2021). "CCK-8 assay manifested that overexpression of RCAN1 remarkably lessened the proliferative ability of liver cancer cells, while overexpression of miR-182-5p and RCAN1 simultaneously diminished the inhibitory effect of RCAN1 overexpression on cell proliferation." (PMID 33959160, 2021). "Further functional experiments exhibited that overexpression of RCAN1 suppressed cell proliferation, migration, invasion, and cell cycle progression of liver cancer." (PMID 33959160, 2021). "As stated by the gene expression data in the TCGA-LIHC dataset, RCAN1 exhibited highly decreased expression in liver cancer tissue." (PMID 33959160, 2021). "In order to investigate the upstream regulatory mechanism of RCAN1 in liver cancer cells, 126 DEmiRNAs containing 122 upregulated and 4 downregulated genes were firstly obtained through bioinformatics analysis in TCGA." (PMID 33959160, 2021). "Then, the results of western blot denoted that the expression of RCAN1 protein in liver cancer cell lines was prominently downregulated as well." (PMID 33959160, 2021). "In this study, reliable data demonstrated that RCAN1 suppressed cell proliferation, migration, invasion, and cell cycle progression of liver cancer." (PMID 33959160, 2021). "Rescue experiments identified that overexpression of RCAN1 conspicuously hindered cell proliferation, migration, invasion, and cell cycle progression of liver cancer, while overexpressing miR-182-5p and RCAN1 simultaneously weakened such inhibitory effect." (PMID 33959160, 2021). "Thus, RCAN1 served as a tumor suppressor to regulate the occurrence and progression of liver cancer." (PMID 33959160, 2021). "Our experimental results also revealed that miR-182-5p could downregulate the expression of RCAN1, thereby facilitating the progression of liver cancer." (PMID 33959160, 2021). "Based on this, it was further proved through cell experiments that miR-182-5p facilitated cell growth of liver cancer through RCAN1 downregulation, showing that RCAN1 may be a fresh biomarker and target for diagnosis and treatment of liver cancer." (PMID 33959160, 2021). "Besides, the inhibitory effect of overexpressed RCAN1 on the migratory ability of liver cancer cells was also revealed by wound healing assay." (PMID 33959160, 2021).
liver cancer (continued). "For instance, this study only substantiated the effects of RCAN1 and miR-182-5p on the proliferation, migration, and invasion of liver cancer cells through in vitro cell experiments, whereas the prognostic value of miR-182-5p for liver cancer patients is not fully verified through clinical studies." (PMID 33959160, 2021). "qRT-PCR and western blot revealed that the mRNA and protein expression levels of RCAN1 in liver cancer cells were notably lower than those in normal human liver cells, indicating that RCAN1 may participate in regulating the progression of liver cancer." (PMID 33959160, 2021). "This study further clarified that RCAN1 could act as a tumor suppressor in liver cancer cells to hamper cell occurrence and progression." (PMID 33959160, 2021). "In this study, we discovered through bioinformatics analysis that RCAN1 was differentially downregulated in liver cancer tissue, and there was a relationship between RCAN1 dysregulation and poor prognosis of patients with liver cancer." (PMID 33959160, 2021). "Next, the Transwell assay was practiced to detect whether RCAN1 regulates the invasion of liver cancer cells, and it came upon that the invasive ability of cells was strikingly reduced with overexpression of RCAN1." (PMID 33959160, 2021). "Additionally, the expression of RCAN1 was noted to be regulated by its upstream regulator miR-182-5p, and miR-182-5p was prominently highly expressed in liver cancer cells." (PMID 33959160, 2021). "This study, to sum up, confirmed that the relationship between miR-182-5p and RCAN1 could affect the progression of liver cancer cells." (PMID 33959160, 2021). "This study investigated the function and mechanism of RCAN1 and miR-182-5p in liver cancer cells." (PMID 33959160, 2021). "RCAN1 overexpressed Hep3b cells were established to study the role of RCAN1 in liver cancer cells." (PMID 33959160, 2021). "Accordingly, probing into the regulatory mechanism of RCAN1 in liver cancer may provide theoretical support for RCAN1 as a cancer regulator." (PMID 33959160, 2021). "Besides, RCAN1 had a notable correlation with the clinical stage of liver cancer." (PMID 33959160, 2021).
liver dysfunction (2 papers, 2021). "In previous studies, RCAN1 has been demonstrated being involved in neurological disease, cardiovascular problems, and liver dysfunction." (PMID 34707090, 2021).
lung carcinoma (2 papers, 2017 to 2023). "The associations between ETS2 and RCAN1 and patient survival in breast and lung cancers were investigated using KM Plotter." (PMID 37107558, 2023). "In conclusion, ETS2 and RCAN1, which are significantly upregulated in DS mouse models, are downregulated in human breast and lung cancers and are associated with patient survival." (PMID 37107558, 2023). "KM Plotter showed that low levels of ETS2 and RCAN1 are associated with poor survival outcomes in breast and lung cancers." (PMID 37107558, 2023). "In this in silico study, we identified two DSCR genes (ETS2 and RCAN1) that are upregulated in DS mouse models but are significantly downregulated in human breast and lung cancer tissues compared to normal tissues and are associated with cancer patient survival." (PMID 37107558, 2023). "RCAN1 reduces the aggressiveness of lung cancer cell lines by inhibiting the calcineurin/NFAT pathway." (PMID 37107558, 2023). "Similar results were observed in the lung cancer cohort, suggesting that ETS2 and RCAN1 expression affect survival outcomes in breast and lung cancers." (PMID 37107558, 2023). "In this study, a positive correlation between ETS2 and RCAN1 was observed in breast and lung cancers." (PMID 37107558, 2023). "Of these genes, ETS2 and RCAN1 were determined to be significantly downregulated in both cancers, suggesting that they may act as tumor suppressors against breast and lung cancers." (PMID 37107558, 2023). "This suggests that RCAN1 acts as a tumor suppressor in lung cancer." (PMID 37107558, 2023). "Considering their expression patterns in DS and breast and lung cancers, as well as their co-expression in these cancers, we hypothesize that ETS2 and RCAN1 are at least partly responsible for the low incidences of breast and lung cancers in DS." (PMID 37107558, 2023). "From this study, RCAN1 levels were associated with patient survival but not cancer stage, suggesting that RCAN1 is associated with the development but not the progression of breast and lung cancers." (PMID 37107558, 2023). "This suggests that ETS2 and RCAN1 are co-expressed and may possess complementary functions in the development of breast and lung cancers." (PMID 37107558, 2023). "GO for molecular function showed that in breast and lung cancers, RCAN1 may be involved in cytokine and glycosaminoglycan binding." (PMID 37107558, 2023). "Altogether, ETS2 and RCAN1 may be essential for the development of breast and lung cancers." (PMID 37107558, 2023). "Down syndrome candidate region-1 (DSCR1, RCAN1), which encodes a protein that suppresses vascular endothelial growth factor (VEGF)-mediated angiogenic signalling via the calcineurin pathway, is a potential candidate for being a tumor suppressor gene for lung cancer." (PMID 28903458, 2017). "A previous study which assessed the frequencies of deleted regions in HSA21 in solid tumors reported that the RCAN1 gene is deleted in Wilms tumors and downregulated (but not deleted) in breast and lung cancers." (PMID 37107558, 2023). "Similarly, ETS2 and RCAN1 expressions were not influenced by lung cancer stages." (PMID 37107558, 2023).
malignant glioma (2 papers, 2017 to 2026). A grade III or grade IV glioma arising from the central nervous system. "Overall, we revealed that RCAN1-4 is a novel TAA for malignant glioma immunotherapy in adult and pediatric patients." (PMID 41436600, 2026). "High RCAN1-4 expression was induced by the binding of the transcription factor C/EBPβ to its transcription start site (TSS) near exon 4 of RCAN1 in malignant glioma, primarily in the mesenchymal GBM subtype." (PMID 41436600, 2026).
melanoma (2 papers, 2024 to 2025). A malignant, usually aggressive tumor composed of atypical, neoplastic melanocytes. "In melanoma, transcript levels of RCAN1 are elevated in comparison to normal samples, indicating that there might be an association to melanoma progression." (PMID 39835134, 2024).
pancreatic cancer (2 papers, 2018 to 2022). "Accordingly, in Pdx-1-Cre; LSL-KrasG12D; Dscr1 transgenic mice, RCAN1 seemed to prevent oncogenesis of pancreatic cancer (driven by oncogenic KrasG12D; P = 0.1161)." (PMID 35717152, 2022).
periodontitis (2 papers, 2016 to 2022). An acute or chronic inflammatory process that affects the tissues that surround and support the teeth. "Expression of RCAN1 was downregulated in total periodontitis tissues compared with total control tissues (RME = 0.17, P-value = 0.01)." (PMID 36090248, 2022). "Expression of RCAN1 was downregulated in total periodontitis tissues compared with total control tissues and in affected tissues obtained from men compared with male control tissue." (PMID 36090248, 2022). "Expression of RCAN1 was downregulated in total periodontitis tissues compared with total control tissues (RME = 0.17, P-value = 0.01) and in affected tissues obtained from men compared with male control tissue (RME = 0.09, P-value = 0.03)." (PMID 36090248, 2022). "However, additional studies in an animal model of periodontitis, for example, RCAN1 knockout mice, are needed to substantiate the importance of RCAN1 in periodontal disease." (PMID 27403036, 2016). "In this study, we assessed the expression of FOS, ITPR, RCAN1, and RGS2 genes in the circulation and affected tissues of patients with periodontitis compared with normal controls." (PMID 36090248, 2022). "To test this hypothesis, we designed this study and measured the expression levels of FOS, ITPR, RCAN1, and RGS2 genes in the affected tissues and the circulation of patients with periodontitis vs. appropriate controls." (PMID 36090248, 2022).
schizophrenia (2 papers, 2017 to 2020). A major psychotic disorder characterized by abnormalities in the perception or expression of reality. "The duplications not currently classified as pathogenic or a VUS in the schizophrenia-LIQ individuals overlapped several interesting neuropsychiatric candidate genes, such as CNTN4, NDUFV2, and RCAN1." (PMID 29187259, 2017).
Sepsis (2 papers, 2017 to 2025). Sepsis is defined as life-threatening organ dysfunction caused by a dysregulated host response to infection. "Additionally, Rcan1 plays a protective role for respiratory infections and sepsis in experimental mice models." (PMID 29104573, 2017).
thyroid cancer (2 papers, 2021 to 2022). "RCAN1, along with metastin—another metastasis suppressor, was found to inhibit thyroid cancer metastasis by reducing the activity of CN-NFAT signaling." (PMID 35717152, 2022). "In head and neck neoplasms, RCAN1 played remarkable biphasic roles in regulation of the progressions of thyroid cancer, oral squamous cell carcinoma (OSCC), hypopharyngeal cancer, and laryngopharynx cancer." (PMID 35717152, 2022). "Metastin/AXOR12 signaling not only suppressed the aggressive tumor phenotype in epithelial ovarian cancer, melanoma, thyroid cancer, esophageal carcinoma, urinary bladder cancer, and gastric carcinoma, but also enhanced the expression of RCAN1." (PMID 35717152, 2022).
Wilms tumor (2 papers, 2015 to 2023). An embryonal neoplasm characterized by the presence of epithelial, mesenchymal, and blastema components. "In particular we found RCAN1 gene in Wilms tumors and a miRNA cluster containing miR-99A, miR-125B2 and miR-LET7C in lung, breast, and melanoma tumors as the main candidates for explaining the inverse comorbidity observed between solid tumors and DS." (PMID 25698970, 2015).
abdominal aortic aneurysm (1 paper, 2013). Enlargement and ballooning of the vessel that supplies arterial blood to the abdomen, pelvis and legs. "Rcan1 additionally plays an essential role in the migration of VSMCs in response to angiotensin II stimulation; moreover, Rcan1 genetic ablation in the mouse confers resistance to abdominal aortic aneurysm and to neointima formation in a restenosis model." (PMID 24127415, 2013).
acute myeloid leukemia (1 paper, 2021). Acute myeloid leukemia (AML) is a group of neoplasms arising from precursor cells committed to the myeloid cell-line differentiation. "Of note, we have identified targets of transcription repressor IKZF1 in MDS cells and acute myeloid leukemia (AML) cells, including G protein-coupled receptor 68 (GPR68) and regulator of calcineurin 1 (RCAN1)." (PMID 34680233, 2021). "We have found that lenalidomide-mediated degradation of IKZF1 leads to activation of the G protein-coupled receptor 68 (GPR68)/calcium/calpain pro-apoptotic pathway and inhibition of the regulator of calcineurin 1 (RCAN1)/calcineurin pro-survival pathway in MDS and acute myeloid leukemia (AML)." (PMID 34680233, 2021). "We have identified signaling molecules downstream of IKZF1, G protein-coupled receptor 68 (GPR68) and regulator of calcineurin 1 (RCAN1) in myeloid malignancies, including MDS and acute myeloid leukemia (AML) with or without del(5q)." (PMID 34680233, 2021).
acute pneumonia (1 paper, 2018). "Complementary studies of a mouse model of P. aeruginosa LPS-induced acute pneumonia confirmed that RCAN1-deficient mice displayed greatly enhanced NF-κB activity and MyD88-NF-κB-mediated cytokine production, which correlated with enhanced pulmonary infiltration of neutrophils." (PMID 29799862, 2018). "To investigate the role of RCAN1 in TLR-MyD88-dependent pathway in vivo, we incorporated RCAN1-deficient mice into a model of P. aeruginosa LPS-induced acute pneumonia." (PMID 29799862, 2018).
adenovirus infection (1 paper, 2015). "Ad-RCAN1.1 and Ad-RCAN1.4 markedly decreased cell viability in 3, 4 and 5 days after adenovirus infection (P<0.0001)." (PMID 26492364, 2015).
adrenal pheochromocytoma (1 paper, 2012). "Recently, overexpression of the RCAN1 protein in the rat adrenal pheochromocytoma cell line, PC12, was reported to enhance the phosphorylation of CREB induced by an adenylate cyclase activator, forskolin." (PMID 23185487, 2012).
amyloidosis (1 paper, 2025). A disorder characterized by the localized or diffuse accumulation of amyloid protein in various anatomic sites. "Thus, the downregulation of RCAN1 observed in oAβ1−42-treated mice could partially account for the previously reported imbalance of the LTP/LTD induction threshold in this amyloidosis murine model, without causing neurodegeneration." (PMID 40414897, 2025).
Anxiety (1 paper, 2020). Intense feelings of nervousness, tension, or panic often arise in response to interpersonal stresses. "Acute pharmacological inhibition of Calcineurin rescued these deficits, while transgenic overexpression of human RCAN1 increased anxiety." (PMID 31918411, 2020). "Rcan1 knockout mice displayed reduced anxiety in several tests of unconditioned anxiety." (PMID 31918411, 2020).
anxiety disorder (1 paper, 2014). A category of psychiatric disorders which are characterized by anxious feelings or fear often accompanied by physical symptoms associated with anxiety. "Thus, the knockdown of the regulator of calcineurin 1 (RCAN1)—a protein regulating the calcium/calmodulin-dependent phosphatase calcineurin implicated in human anxiety disorders—increased in mice pCREB and BDNF levels." (PMID 25505876, 2014).
Aortic dissection (1 paper, 2018). Aortic dissection refers to a tear in the intimal layer of the aorta causing a separation between the intima and the medial layers of the aorta. "Our data also show that aortic homeostasis depends on Rcan1 expression in both SMCs and ECs, because its specific deletion in either cell type predisposed to lethal aortic dissection and IMH formation." (PMID 30442942, 2018).
Aortic Rupture (1 paper, 2018). The tearing or bursting of the wall along any portion of the AORTA, such as thoracic or abdominal. "Together, these data indicate that, contrary to constitutive Rcan1 genetic inactivation, its conditional deletion promotes a hypercontractile phenotype in aortic SMCs that predisposes to aortic rupture and IMH." (PMID 30442942, 2018).
arterial diseases (1 paper, 2014). "In conclusion, RCAN1 is a potential proatherogenic factor, and its regulation may contribute to the prophylaxis of different arterial diseases." (PMID 25713607, 2014).